PKM (pyruvate kinase M1/2)
Diseases named in the same sentence as PKM in open-access papers (continued):
Sharing a sentence is not in itself a finding about the gene and the disease.
cancer (continued). "Recent findings showed lncRNA small nucleolar RNA host gene 3 (SNHG3) functioned as an endogenous sponge for miR-330, thereby modulating the expression of pyruvate kinase M1/2 (PKM), which led to a down-regulation in cancer cell mitochondrial activity and promoted cancer growth and glycolysis." (PMID 32957712, 2020). "Meanwhile, PKM is subjected to splicing and generates two isoforms: PKM1, expressed in brain, bladder, adult muscle, and fibroblasts; and PKM2, expressed in tissues during embryogenesis and upregulated in multiple cancers." (PMID 32585931, 2020). "For example, mTOR activation in cancer cells upregulates the expression of PKM2 through HIF-1α mediated transcriptional activation of PKM, and Myc-hnRNPs-mediated splicing of PKM pre-mRNA, in favor of PKM2." (PMID 30857125, 2019). "For example, the embryonic isoform M2 (PKM2), a known interactor of HSP90 resulting from an alternative splicing of PKM pre-mRNA, is a pivotal regulator of the Warburg effect, and is over-expressed in different types of cancer." (PMID 31163702, 2019). "In addition, oleanolic acid inhibited aerobic glycolysis by inducing pyruvate kinase muscle (PKM)isoforms switch from PKM2 to PKM1 through suppression of phosphorylated mTOR, consequently disrupting Warburg effects in various cancer cells." (PMID 28300756, 2017). "It is important to note that PrECs exhibited the highest PKM activity among cell lines used in this study and the cell growth rate in mesenchymal cancer cells is less than the epithelial cancer cells (data not shown)." (PMID 25426557, 2015). "Decreased glycolytic flux may play a role, including downregulation of PKM2, an isoform of PKM specifically overexpressed in cancers, in the absence of IGF2BP3." (PMID 41015030, 2025). "Five enzymes involved in glycolysis present only or mainly in sEVs isolated from cancer-derived cell lines were validated: aldolase (ALDOA), glyceraldehyde-3-phosphate dehydrogenase (GAPDH), phosphoglycerate kinase (PGK1), enolase (ENO) and pyruvate kinase (PKM)." (PMID 37189694, 2023). "Furthermore, increased cancer-like PKM isoform switching was also evident in RNA-seq from 633 PM prefrontal cortex samples across Braak stages, as PKM1 levels were decreased and PKM2 levels increased at the time of death in patients diagnosed with AD." (PMID 35987203, 2022). "Interestingly, it was seen that iHCC1 and iHCC2 cluster tumours use liver-specific PKLR for the utilisation of pyruvate rather than the muscle isoform PKM, signifying metabolic dysregulation on multiple pathways, indicative of more advanced or aggressive cancer." (PMID 32201876, 2021). "However, it has been observed that it is not the only isoform of PKM overexpressed in cancer." (PMID 33809480, 2021). "This weakens PKM metabolic activity and the non-metabolic PKM2/β-catenin signaling pathway, which in turn inhibits cancer cells from utilizing glycolysis and proliferating." (PMID 38785973, 2024). "The potential of PKM2 and not PKM1 to mediate the Warburg effect was suggested when the alternatively spliced isoform (PKM1) from the PKM gene, failed to activate HIF-1 in cancer cells." (PMID 25768091, 2015). "In some cancer cells, PTBP1 could promote PKM splicing to PKM2 rather than PKM1, thus leading to a metabolic shift from OXPHOS to glycolysis." (PMID 36508323, 2023). "PKM expression in the normal liver is rather low in all the normal tissues studied and the extent of PKM2enrichment between tumor and control is higher in HCC than in majority of cancers from other tissues." (PMID 26147004, 2015).
tumor (1,170 papers, 2006 to 2026). "Our analysis revealed differences in the glycolysis-related gene signature score across gender, grade stage, tumor stage, and T stage, while only PKM expression was found to be associated with age." (PMID 41206438, 2025). "PKM is expressed as two isoforms that result from mutually exclusive alternative splicing events; PKM1 is expressed mainly in quiescent cells, while PKM2 has been linked to the Warburg effect in tumor cells." (PMID 38233562, 2024). "In sum, specific loss of PKM isoform reveals differential roles in cell cycle regulation and tumour cell growth." (PMID 34240779, 2021). "The PKM subtype can be switched from PKM1 to PKM2 in rapidly proliferating tumor cells, which is involved in the loss of pyruvate kinase activity." (PMID 32467671, 2020). "It is believed that PKM isoform expression and changes of PK activity are associated with increased tumor growth rates." (PMID 31423225, 2019). "It is believed that PKM isoform expression and activity change with tumor progression are linked to an increased tumor growth rate." (PMID 29629339, 2018). "The number of normal and tumor samples, and the expression levels of each transcript variant of PKM in each tissue type are also shown." (PMID 25738776, 2015). "Moreover, PKM upregulation was linked to advanced tumor stage (T3/T4, p = 0.02) and vascular invasion (p = 0.01)." (PMID 40678800, 2025). "A major advance in our understanding of the factors that regulate tumor cell metabolism was the discovery that the tumor-associated shift to aerobic glycolysis was controlled by the balance of expression of 2 isoforms of the glycolytic enzyme pyruvate kinase M (PKM)." (PMID 23451252, 2013). "Systemic delivery of antisense oligonucleotides (ASOs) that shift PKM splicing from the PKM2 isoform to the PKM1 isoform inhibits tumor progression and reprograms intratumoral metabolism." (PMID 42009652, 2026). "The alternative splice isoform of pyruvate kinase M (PKM), PKM2, plays a pivotal role in regulating aerobic glycolysis in tumor cells." (PMID 42009652, 2026). "Recent studies have demonstrated that METTL1-mediated m7G modification of PKM mRNA enhances PKM2 protein expression, thereby promoting tumor progression and glycolytic activity." (PMID 41562049, 2025). "Meanwhile, subgroup analysis showed that abnormal PKM expression correlated with age, tumor size, tumor differentiation, vascular invasion, tumor embolus, ALT, AFP, and clinical stage." (PMID 41206438, 2025). "Glycolysis-induced lactate production promoted P300-mediated lactylation of HNRNPA1 at lysine 350, which facilitated PKM pre-mRNA splicing toward the PKM2 isoform, enhancing glycolytic flux and supporting tumor growth." (PMID 41275207, 2025). "(i) Prediction of tumor type and progression: The expression level of PKM proteoform is different in different types and grades of OC." (PMID 40137167, 2025). "It is worth mentioning that several reports have shown elevated levels of these gluconeogenesis-related genes, especially ENO1, PGK1, and PKM, in tumor tissues." (PMID 40821334, 2025). "In the context of tumor progression, mutually exclusive splicing events such as PKM (metabolism) and FGFR (EMT) display how splice switching often favors aggressive tumor progression." (PMID 41150697, 2025). "miR-340 is involved in tumor suppression in CRC by modulating alternative splicing of the PKM gene or specifically targeting RLIP76." (PMID 40806335, 2025). "Studies were selected based on relevance to the topic and their contribution to the understanding of PKM in the tumor microenvironment." (PMID 40137167, 2025). "Within the glycolysis pathway, genes such as HK2, PFKP, and PKM displayed elevated expression, thereby emerging as prospective targets warranting exploration for restraining tumor cell glycolytic activity." (PMID 38414015, 2024).
tumor (continued). "In the PPI results, we observed that molecules such as MAPK14, ATP6V1, Itgbs, MB2, STAT3, PKM, ACSS3, and MYL9, which are associated with signal transduction, inflammation, and tumor invasion, exhibited more active interactions with other molecules." (PMID 38203782, 2024). "Differential analysis indicated that SLC16A3+ macrophages exhibit high expression of macrophage markers promoting migration, invasion and tumour angiogenesis, such as SPP1 and MMP9, as well as genes associated with glycolysis, including PKM." (PMID 39656344, 2024). "In fact, it has been shown for the CPTAC patient cohort that PGK1 and PKM have increased phosphorylation when comparing tumour versus normal." (PMID 39633487, 2024). "Alternative splicing of one of those isoforms, PKM, results in PKM2, which is exclusively expressed by tumor cells." (PMID 39329757, 2024). "First, we examined the mRNA levels of PKs and ENOs, and found that PKM and ENO1 were the predominantly transcribed genes of these two families in tumor cells, that encodes PKM1, PKM2 and ENO1." (PMID 38750259, 2024). "The pyruvate kinase M (PKM) gene is mainly present in tumors in the form of PKM2, a key glycolytic enzyme that can influence tumor glycolysis and a variety of tumor biological behaviors." (PMID 35924724, 2023). "For example, PKM (increased in FLC tumor log2 = 0.95) is often a rate limiting enzyme in glycolysis, driving tumorigenesis." (PMID 37343102, 2023). "In an in vivo assay using a xenograft mouse model, the promotion of tumor growth induced by ESRRG knockdown was partially offset by the silencing of PKM." (PMID 37679788, 2023). "Based on TCGA-LIHC, there was high expression of FSTL3 and PKM in the HCC tumor samples compared with the controls (P < 0.05)." (PMID 38044354, 2023). "SNHG3 sponges hsa-miR-330-5p in tumor cells that positively regulate PKM, thereby increasing tumor growth." (PMID 37629204, 2023). "Protein expressions of HK2, PFKM and PKM were found to be high in tumor tissues with cytoplasmic localization." (PMID 35328104, 2022). "SRSF3 recognizes and enhances the inclusion of the exon 10 of the pyruvate kinase M (PKM) that plays a crucial role in regulating the Warburg effect, favoring the M2 isoform that promotes aerobic glycolysis and tumor growth." (PMID 36140826, 2022). "In summary, base editing was successfully applied to perturbate endogenous PKM splicing in cultured tumour cells and zebrafish model, and PKM1‐ or PKM2‐specific functions and modulated genes were generally described." (PMID 34240779, 2021). "Firstly, PKM mRNA expression profile across all tumor samples and paired normal tissues was obtained through GEPIA database and the protein expression in normal tissues and cell lines for PKM was obtained through GeneCards database." (PMID 34234853, 2021). "For example, PTBP1 enhances the PKM2 isoform and reduces the PKM1 isoform by controlling PKM alternative splicing, which promotes aerobic glycolysis and provides a selective advantage for tumor formation." (PMID 34706749, 2021). "In a similar context, both pyruvate kinase PKM and Fructose-bisphosphate aldolase A play important roles in glycolysis and are therefore also crucial for tumour cell proliferation." (PMID 34832109, 2021). "Our 2D-PAGE analysis showed differential expression of spots containing PKM fr in the central part and 1D-WB analysis showed perturbation of the expression in the peripheral part of the tumor." (PMID 34563043, 2021). "Biologically, Let-7a suppresses the Myc/HnRNPA1/PKM axis, which further modulates tumor growth and motility." (PMID 35008539, 2021). "PKM also acts as protein kinase, which shifts the glucose metabolism from the respiratory chain to aerobic glycolysis in tumor cells." (PMID 33767290, 2021). "The increased expression of c-Myc promoted alternative splicing of PKM to PKM2, resulting in the metabolic reprogramming of tumor cells." (PMID 34930376, 2021).
tumor (continued). "Of note, the gene PKM.1 can give rise to many isoforms but only PKM2 is expressed in tumour cells where it alters glucose metabolism; thus, we selected PKM2 for the validation of PKM." (PMID 32183388, 2020). "The muscle type of pyruvate kinase (PKM) is one of the key mediators of the Warburg effect and tumor metabolism and was closely related to the development of PSE meat." (PMID 32695825, 2020). "Mechanistically, SNHG3 knockdown in CAF-secreted exosomes suppressed glycolysis metabolism and cell proliferation by the increase of miR-330-5p and decrease of PKM expression in tumor cells." (PMID 31956955, 2020). "Studies have shown that PKM2 is the key enzyme of the aerobic glycolysis of the tumour cells as one of the four isoforms of PKM, which is known as a regulator of glycolysis in malignant tissues." (PMID 32476531, 2020). "In turn, increased PTBP1 levels induce a shift in the AS of tumor-associated transcripts, namely, the small GTPase Ras-related C3 botulinum toxin substrate 1 (RAC1), adaptor protein NUMB, and PKM." (PMID 33261131, 2020). "Alternative splicing of the pyruvate kinase M (PKM) can produce the pyruvate kinase muscle 2 (PKM2) isoform and promote aerobic glycolysis and tumor growth." (PMID 33072610, 2020). "The higher DNA methylation at exon-10 of PKM-gene correlates with the inclusion of exon-10 in tumor tissue compared with the paired normal." (PMID 31675998, 2019). "Induction of PKM2 tetramerization, which inhibits PKM-2 targeted gene expression, reduced the expression of PD-L1, suggesting that the hypoxic tumor microenvironment promotes widespread PD-L1 expression through PKM2." (PMID 29081778, 2017). "Muscle type of pyruvate kinase (PKM) is one of the key mediators of the Warburg effect and tumor metabolism." (PMID 25738776, 2015). "It was previously thought that tumor cells switch expression of PKM from normal tissue-expressed PKM1 to tumor-specific PKM2 via an alternative splicing mechanism." (PMID 24077665, 2014). "A heatmap showing M value differences of the PKM gene between various normal and tumor tissues also suggested that cg24327132 and the nearby cg12433486 were two probes consistently hypermethylated in normal tissues and became demethylated in tumors." (PMID 24077665, 2014). "Tumor formation therefore appears to involve alterations in PKM isoform expression, accompanied by a tumor-promoting shift in PK activity and metabolism from oxidative phosphorylation to aerobic glycolysis." (PMID 23451252, 2013). "The proteomic study found that total PKM expression (PKM1 + PKM2) is increased 3-fold in tumor tissue compared to normal tissue." (PMID 21709315, 2011). "Under different pathophysiological conditions, PTMs, alternative splicing, conformational changes, binding partners, subcellular localization and other factors promote the formation of different PKM proteoforms to promote tumor development through their respective functions and pathways." (PMID 40137167, 2025). "Taken together, ALDOA and PKM may be critical targets for a novel anti-tumor approach in combination withTUG1 silencing to prevent HCC progression." (PMID 40696822, 2025). "The chemical essence of PKM is a protein, and its activity is regulated by PTMs, allosteric effectors, and hormonal signaling pathways, which subsequently affect the proliferation, invasion, and angiogenesis of tumor cells." (PMID 40137167, 2025). "The pro-tumor regulatory effect exhibited by TGF-β in situations of hypoxia or advanced tumors may be regulated by the PKM isoforms." (PMID 40943648, 2025). "This patient’s tumor metabolism suggests an adaptive survival program, boosting glycolytic flux via PKM and PGK1 to meet energetic and biosynthetic demands, while downregulating ribosomal machinery to conserve resources, potentially in an mTOR-influenced and immune-suppressive context." (PMID 41367869, 2025).
tumor (continued). "Our qRT‐PCR experiments further revealed that METTL3 may promote the glycolysis capacity of ESCA cells by upregulating the expression of glycolysis‐related genes SLC2A1, GPI, PFKL, PGK1, ENO1 and PKM, thus facilitating tumour cell proliferation and migration." (PMID 38429907, 2024). "Furthermore, PKM expression was found to increase with tumor stage progression, indicating its potential involvement in the advancement of HCC." (PMID 39070142, 2024). "It is unknown whether activating or inhibiting PKM is effective in the treatment of cancer because tumor cells show greater benefit from low PKM2enzyme activity." (PMID 36755301, 2023). "The significance of PKM, a key enzyme in the final rate-limiting step of glycolysis, in tumor cell metabolism has now been extensively studied, whereas the potential function of FSTL3, an oncogene that has recently piqued the interest of researchers, in HCC has not been elucidated." (PMID 38044354, 2023). "In a more recent study involving the two isoforms of the PKM (Pyruvate Kinase M1/2) gene, ASOs were used in one case (PKM1 isoform, a tumor suppressor) to restore its expression, and in the other (PKM2 isoform, an oncogene) to decrease it, resulting in reduced tumor growth." (PMID 37834310, 2023). "Besides its crucial role in metabolic reprogramming, PKM also serves as a cytosolic thyroid hormone receptor and epigenetic regulator of gene transcription in tumor cells." (PMID 37612452, 2023). "To investigate whether the inhibition of glycolysis activity and tumor growth by ESRRG is mediated through PKM, we performed knockdown of PKM in ECa109 and KYSE510 cells." (PMID 37679788, 2023). "Interestingly, although a switch from PKM1 to PKM2 regulated by the alternative splicing of PKM was observed in many types of tumor, PKM2 was the prominent isoform of PKM both in normal liver and HCC." (PMID 37566009, 2023). "Furthermore, PKM2/PKM play a crucial role in regulating cell cycle and tumor metabolism, including glycolysis." (PMID 36276080, 2022). "Hence, the regulation of PKM alternative splicing is crucial for understanding tumor metabolic regulation." (PMID 33670011, 2021). "In the differential expression analysis between high- and low-expressing ACSS1 HCC tumours, it was seen that high ACSS1 was associated with the suppression of FAO and increased PKM, a combination that has been previously linked to hypoxia and de-differentiation in HCC." (PMID 32201876, 2021). "Pyruvate kinase M (PKM) is a glycolytic enzyme required for tumor proliferation and progression." (PMID 34869385, 2021). "IHC staining of PKM isoforms in these in vivo tumor samples were observed to be correlating with western blot results suggesting higher expression of PKM1 isoform and depleted expression of PKM2 isoform in SMAR1 overexpressing tumors compared with that of control tumors." (PMID 33863392, 2021). "Therefore, the function of alternative splicing products of PKM in tumor oncogenesis and progression remains controversial." (PMID 33478099, 2021). "PTBP1 increases the ratio of the PKM2/PKM1 variant by binding intron 8 of PKM and elevating the PKM2 transcript variant with exon 9 skipping, thereby enhancing the Warburg effect and promoting tumor progression." (PMID 34330892, 2021). "As high glycolysis is necessary for tumor growth and survival, a decrease in PKM/PKM with P4 may be an important mechanism of growth suppression." (PMID 32590878, 2020). "PKM plays a role in caspase independent cell death in tumor cells." (PMID 33615312, 2020). "It speculated that the upregulated expression of CLU, GNAS, and PKM may inhibit the occurrence of tumor in the early stage, while the expression decreased in the late-stage promotes the development of tumor." (PMID 33299887, 2020). "In summary, these results demonstrated that CLU, GNAS, and PKM are differentially expressed in the serum of MF patients and normal subjects, which may inhibit the occurrence and development of tumor directly/indirectly." (PMID 33299887, 2020).